ZNF776 (zinc finger protein 776)
Description:
May be involved in transcriptional regulation.
Synonyms: FLJ38288
Tractability: PROTAC: UniProt records ubiquitination sites on it; ubiquitination databases record sites on it.
Gene: Protein-coding gene on chromosome 19 (57,746,815 to 57,758,148, forward strand). Ensembl gene ENSG00000152443.
Subcellular location: Nucleus
Subcellular location (Human Protein Atlas): Nucleoplasm; Cytosol
Pathways (Reactome):
Gene expression (Transcription): Generic Transcription Pathway
Gene Ontology:
Molecular function: protein binding; DNA-binding transcription factor activity, RNA polymerase II-specific; RNA polymerase II cis-regulatory region sequence-specific DNA binding
Biological process: regulation of transcription by RNA polymerase II; negative regulation of DNA-templated transcription; regulation of DNA-templated transcription
Cellular component: nucleus
Genetic constraint (gnomAD): Loss-of-function variants: 3 observed, 6.26 expected, observed/expected ratio (o/e) 0.48, 90% interval 0.22 to 1.23. That is too few expected variants to judge how well the gene tolerates losing a copy. Missense variants: 545 observed, 638.27 expected, observed/expected ratio (o/e) 0.85, 90% interval 0.8 to 0.92. Synonymous variants: 201 observed, 216.41 expected, observed/expected ratio (o/e) 0.93, 90% interval 0.83 to 1.04.
Homologues: Orthologues: chimpanzee ZNF776 (99% identical). Paralogues in human: ZNF417 (57% identical), ZNF587 (57% identical), ZNF416 (52% identical), ZNF530 (47% identical), ZNF17 (47% identical), ZNF34 (37% identical), ZNF287 (36% identical), ZNF547 (36% identical), ZNF527 (35% identical), ZNF214 (35% identical), ZNF285 (34% identical), ZKSCAN7 (33% identical), and 38 more.
Diseases named in the same sentence as ZNF776 in open-access papers:
ZNF776 is named in the same sentence as 1 disease in open-access papers, as found by Europe PMC text mining. Sharing a sentence is not in itself a finding about the gene and the disease. The quoted sentences say what the papers report.
allergic rhinitis (1 paper, 2014). Inflammation of the nasal mucous membranes caused by an IgE-mediated response to external allergens. "We found that the 19q13.43 locus near ZNF776 was associated with allergic rhinitis (GWAS P value 5.0 × 10−8) as well as CD4+ gene expression (χ2 = 19.55, FDR-adjusted P value 0.00078)." (PMID 25085501, 2014).